LPIN1 (lipin 1)
Diseases named in the same sentence as LPIN1 in open-access papers (continued):
Sharing a sentence is not in itself a finding about the gene and the disease.
Hypertension (2 papers, 2014 to 2024). The presence of chronic increased pressure in the systemic arterial system. "Furthermore, CTDNEP1 is known to dephosphorylate LPIN1, which is implicated in the development of hypertension." (PMID 39189255, 2024).
liver cancer (2 papers, 2023). An epithelial or non-epithelial malignant neoplasm that arises from the liver. "The DSS analysis results displayed that liver cancer patients with high expression of ATF3, ACSL1, and LPIN1 exhibited significantly longer DSS." (PMID 37580343, 2023). "By analyzing RNA-seq data from TCGA and GTEx, we discovered that ATF3, ACSL1, LPIN1, and DDR2 were significantly downregulated while DDIT3 was upregulated in liver tumor compared with normal tissues, implying that these five genes might be associated with liver cancer." (PMID 37580343, 2023). "Notably, G6PD, FASN and LPIN1 are upregulated in HCC compared with non-tumor livers in both HCC cohorts while ETFDH is downregulated, highlighting the likely role of lipid metabolism and PPP pathways in liver cancer." (PMID 37301960, 2023).
metabolic myopathies (2 papers, 2019 to 2023). "LPIN1 is the major culprit in metabolic myopathies, mitochondrial diseases, abnormal lipid metabolism, and inflammation." (PMID 37346041, 2023).
Myalgia (2 papers, 2020 to 2021). "About 41.7% and 33.3% of the LPIN1 mutations result in myasthenia and myalgia respectively." (PMID 33456573, 2021).
ovarian carcinoma (2 papers, 2021 to 2022). A malignant neoplasm originating from the surface ovarian epithelium. "In ovarian cancer, the expressions of mir584 and of lipin-1 are regulated in opposite directions, and depleting the cells of mir584 induces an increase in lipin-1 expression, resulting in increased tumorigenesis." (PMID 33922580, 2021). "Similarly, Yang and Ma reported that mir584 regulates ovarian cancer progression by targeting lipin-1." (PMID 33922580, 2021).
acute myocardial infarction (1 paper, 2018). Necrosis of the myocardium, as a result of interruption of the blood supply to the area. "Previous reports have indicated that the miR-122-5p/miR-133b ratio could as a specific early prognostic biomarker for acute myocardial infarction, and miR-122-5p upregulation can trigger the compensatory response of LPIN1 and CTDNEP1 in hepatosteatosis." (PMID 29467645, 2018).
alcoholic liver diseases (1 paper, 2016). A disorder caused by damage to the liver parenchyma due to alcohol consumption. "Lipin-1 has been implicated in the pathogenesis of alcoholic liver disease (ALD)." (PMID 27666676, 2016).
Cachexia (1 paper, 2024). Severe weight loss, wasting of muscle, loss of appetite, and general debility related to a chronic disease. "Notably, expression of genes involved in the regulation of metabolic activities, including Pik3r1, Pdk4, Foxo1, Rorc and Lpin1, increased in type IIb myonuclei upon cachexia." (PMID 39001644, 2024).
cardiac hypertrophy (1 paper, 2021). "After transverse aortic constriction–induced pressure overload, loss of lipin 1 did not exacerbate cardiac hypertrophy or dysfunction." (PMID 33986192, 2021).
cervical adenocarcinoma (1 paper, 2015). An adenocarcinoma arising from the cervical epithelium. "Hypoxia has been observed to increase triglyceride accumulation in lipid droplets through increased Lipin 1 expression in a HIF-1α dependent mechanism, as shown in HeLaM cervical adenocarcinoma and Huh7 human hepatoblastoma cells." (PMID 26305551, 2015).
channelopathies (1 paper, 2020). "In subject 2.1 and 2.2 focused single gene analysis comprised NGS panel for genes associated with channelopathies, Long QT syndrome, DMD, LPIN1, and RYR1 were negative." (PMID 31339582, 2020).
colitis (1 paper, 2021). Inflammation of the colon. "They elegantly demonstrated that, in a model of colitis-associated tumors, lipin-1-deficient animals developed fewer and smaller tumors than their littermate controls." (PMID 33922580, 2021). "The graft of WT macrophages into lipin-1-deficient mice, or their treatment with the pro-inflammatory interleukin 23, increased colitis burden." (PMID 33922580, 2021).
congenital generalized lipodystrophy type 2 (1 paper, 2025). Any congenital generalized lipodystrophy in which the cause of the disease is a mutation in the BSCL2 gene. "Furthermore, the ER-localized 1 AGPAT-2 and lipin 1 proteins can directly interact with the ER-localized seipin protein, which is related to Congenital Generalized Lipodystrophy type 2 (CGL2)." (PMID 40508223, 2025).
developmental delay (1 paper, 2026). "Emerging experimental and clinical evidence suggests a potential biological link between LPIN1 dysfunction, impaired myelination, and abnormal neurodevelopment, raising the possibility that developmental delay may be an under-recognized phenotypic feature of this condition." (PMID 42220764, 2026).
dilated cardiomyopathy (1 paper, 2021). Cardiomyopathy which is characterized by dilation and contractile dysfunction of the left and right ventricles. "LPIN1, PPP1R3C, PTPN1, CREM, and NR0B2 were identified as the main effectors in metabolism dysregulation in the remote zone and were found differentially expressed also in the myocardium of patients with ischemic and/or dilated cardiomyopathy." (PMID 34722683, 2021).
fatty acid metabolic disorder (1 paper, 2023). "circRNA_021412/miR-1972/LPIN1 signal may be the key factor affecting circRNA-related fatty acid metabolic disorder, resulting in adipogenesis." (PMID 37791070, 2023). "circRNA_021412/miR-1972/LPIN1 signal might be a key factor in circRNA-related fatty acid metabolic disorder, resulting in increased adipogenesis." (PMID 37791070, 2023).
glioblastoma (1 paper, 2021). The most malignant astrocytic tumor (WHO grade IV). "In mouse myoblast C2C12 and human primary glioblastoma U87 cells, LPIN1 siRNA achieved > 70% knockdown efficiency, resulting in abnormal expression levels of muscular and neuronal markers." (PMID 33456573, 2021). "The conservatism of the molecular pathways regulated by lipin 1 was evaluated in human primary glioblastoma and mouse myoblast cells by siRNA knockdown, drug treatment, qRT-PCR and Western blotting analysis." (PMID 33456573, 2021). "To further substantiate the influence of LPIN1 on NOTCH signaling, we carried out siRNA knockdowns of LPIN1 in HEK293T, human primary glioblastoma U87, mouse myoblast C2C12, and human osteosarcoma U2OS cells, respectively." (PMID 33456573, 2021).
invasive breast carcinoma (1 paper, 2020). A carcinoma that infiltrates the breast parenchyma. "Moreover, we evaluated the correlation of p-Tyr795-lipin-1 with patient survival in a cohort of specimens from another 60 patients with invasive breast cancers for which the information of overall survival and relapse-free survival were available." (PMID 33203880, 2020).
leukemia (1 paper, 2025). A malignant (clonal) hematologic disorder, involving hematopoietic stem cells and characterized by the presence of primitive or atypical myeloid or lymphoid cells in the bone marrow and the blood. "Together, these data pointed toward a functional role of LPIN1 in leukemia warranting further investigation in primary human samples." (PMID 40265168, 2025).
lung carcinoma (1 paper, 2022). "The involvement of LPIN1 in gefitinib resistance was further validated using lung cancer patient-derived cells (PDCs) YL05." (PMID 35565351, 2022). "In this study, we propose LPIN1 as a factor regulating gefitinib resistance in EGFR-mutant lung cancer cells, which upon depletion, results in synthetic lethality with gefitinib treatment." (PMID 35565351, 2022). "Unlike TKI-sensitive HCC827 cells, the intracellular level of LPIN1 was transcriptionally induced by gefitinib treatment in TKI-resistant H1650 and patient-derived TKI-resistant lung cancer cells." (PMID 35565351, 2022). "We confirmed that LPIN1 depletion increased gefitinib sensitivity in drug-resistant H1650 NSCLC cells, as well as patient-derived YL05 lung cancer cells." (PMID 35565351, 2022). "Knowing that DAG induces PKC activation, we compared the relationship between LPIN1 expression and PKC activation in gefitinib-sensitive and gefitinib-resistant lung cancer cells." (PMID 35565351, 2022).
mastitis (1 paper, 2020). Inflammation of breast tissue during lactation or postpartum due to an obstructed duct or infection. "Some of the highly connected genes in the purple module have previously been related to mastitis development including NFKBIZ, NFKBIA, CXCL2, GRO1, CXCL3, LPIN1, and DAB2." (PMID 32754201, 2020).
metastasis (1 paper, 2020). The spread or migration of cancer cells from one part of the body (where they first appeared) to another. "Importantly, statistical analyses show that levels of p-Tyr-lipin-1 correlate with tumour sizes, lymph node metastasis, time to recurrence and survival of the patients." (PMID 33203880, 2020).
multiple acyl-CoA dehydrogenase deficiency (1 paper, 2024). "Lipid storage myopathies can be caused by genetic variants in genes that encode enzymes involved in muscle fatty acid metabolism and include among others neutral lipid storage disease, lipin-1 deficiency, carnitine deficiency, and multiple acyl-CoA dehydrogenase deficiency (MADD)." (PMID 39586906, 2024).
myasthenia (1 paper, 2021). "In this study we identified two novel compound heterozygous variants, c.2047A>C (p.I683L) and c.2201G>A (p.R734Q) of LPIN1 from a syndromic myasthenia family." (PMID 33456573, 2021). "2201G>A (p.R734Q) in LPIN1, which caused adult-onset syndromic myasthenia." (PMID 33456573, 2021). "Herein, two novel compound heterozygous mutations in LPIN1 with neurological disorders, but no myoglobinuria were identified in an adult-onset syndromic myasthenia family." (PMID 33456573, 2021).
parasitic infections (1 paper, 2020). "Future work will be needed to better understand the mechanisms by which lipin-1 transcriptional co-regulator activity drives macrophage function in different pathological conditions of sterile inflammation and parasitic infections." (PMID 32431707, 2020).
skin cancer (1 paper, 2020). "Thus, our data suggest that lipin-1 inhibition is a novel target for the prevention of UVB radiation-induced production of proinflammatory cytokines that lead to photoaging and skin cancer." (PMID 32080341, 2020).
ZIKV infection (1 paper, 2022). "Additionally, ZIKV infection of moDCs upregulated LPIN1, which catalyzes the conversion of phosphatidic acid to diacylglycerol, a key precursor for the synthesis of triglyceride, phosphatidylcholine, and phosphatidylethanolamine." (PMID 36097162, 2022).
tumor (16 papers, 2015 to 2024). "High levels of Lipin-1 expression are associated with a poor prognosis and inflammation, and downregulation of Lipin-1 induces ER stress and apoptosis and attenuates tumor growth in xenograft mouse models." (PMID 33530546, 2021). "Importantly, p-Tyr795-lipin-1 was positively associated with tumour volume, with a significant linear trend identified across the levels of lymph-node metastasis and the clinical stages of the patients." (PMID 33203880, 2020). "Consistent with in vitro results, LPIN1 knockdown or inhibitor treatment rarely affected tumor growth compared with the control group." (PMID 35565351, 2022). "As a tumor suppressor, exosomal miR-451a targets LPIN1 to suppress hepatocellular tumorigenesis by regulating tumor cell apoptosis and angiogenesis." (PMID 35280805, 2022). "Further studies are, however, required in order to fully understand how host lipin-1, but also host lipin-2 and -3, can alter the tumor microenvironment." (PMID 33922580, 2021). "In this review, we will focus on the most recent research describing the roles of lipin-1 in tumor progression, illustrating the interest in its inhibition to supplement other anti-cancer therapies." (PMID 33922580, 2021). "Here, we will review the most recent research describing the role of lipin-1 in tumor progression when expressed by cancer cells or cells of the tumor microenvironment." (PMID 33922580, 2021). "We next employed the mice expressing the Polyoma Virus middle T antigen under the direction of the mouse mammary tumour virus promoter/enhancer (MMTV-PyVT) to investigate the effect of lipin-1 in tumour development." (PMID 33203880, 2020). "We show that the metastatic potential of WT MMTV tumour cells is reduced in Lpin1−/− mice compared to Lpin1+/+ mice, and the non-tumour effect of lipin-1 contributes to 8.89% of the total variance in metastasis." (PMID 33203880, 2020). "While WT tumour cells exhibited stronger metastatic potential in Lpin1+/+ mice, Lpin1-KO tumour cells showed equally low metastasis in either Lpin1+/+ or Lpin1−/− mice." (PMID 33203880, 2020). "Mice injected with tumour cells expressing 3YF-lipin-1 showed a much lower incidence of lung metastasis and reduced lung seeding compared to mice injected with WT-lipin-1-expressing or control tumour cells." (PMID 33203880, 2020). "The xenografts that expressed 3YF-lipin-1 grew significantly slower than WT-lipin-1-expressing tumours." (PMID 33203880, 2020). "To clarify this, we transplanted WT and Lpin1-KO MMTV tumour cells separately into Lpin1+/+ or Lpin1−/− mice." (PMID 33203880, 2020). "In in vivo tumorigenesis assay, we identified that both shRNA-mediated depletion and pharmaceutical inhibition of LPIN1 clearly reduced tumor growth and confirmed that gefitinib treatment induced LPIN1 expression and LPIN1-dependent NF-κB activation (an increase in p-IκBα level) in tumor tissues." (PMID 35565351, 2022). "However, gefitinib treatment combined with LPIN1 depletion or inhibition, significantly inhibited tumor growth compared to treatment with gefitinib alone." (PMID 35565351, 2022). "Additionally, we validated that targeting LPIN1 synergistically retarded tumor growth in an in vivo mouse xenograft model." (PMID 35565351, 2022). "LPIN1 plays a critical role in cancer progression, and its expression is increased in various cancer cells, indicating its role in cell proliferation and tumor growth." (PMID 35565351, 2022). "Although our proteomics analyses did not cover the related proteins, recent data have demonstrated that lipin-1 may amplify the inflammatory process, thereby promoting carcinogenesis and tumor progression." (PMID 35832080, 2022). "Since Rac1 is often overexpressed and/or overactivated in cancers, the hypothesis that lipin-1 may be involved in tumor biology was raised." (PMID 33922580, 2021). "Meanwhile, the tumour frequency or tumour onset was also not significantly affected by lipin-1 deficiency." (PMID 33203880, 2020).
tumor (continued). "Moreover, we also identified a strong correlation of the activation of the Src–lipin-1 axis with tumour malignancy and poorer prognosis." (PMID 33203880, 2020). "However, one question remains in this study is whether lipin-1 in non-tumour cells also functions to shape pro-metastatic microenvironment." (PMID 33203880, 2020). "Moreover, depletion of lipin-1 significantly retarded tumour growth of the orthotopic xenografts." (PMID 33203880, 2020). "However, it is formally possible that germline deletion of lipin-1 could also affect non-tumour cells, which in turn alter tumour metastasis." (PMID 33203880, 2020). "Lipin-1, a member of the lipin family, was reported to be overexpressed in various cancer types and its silencing or inhibition prevents cancer cells proliferation in vitro and tumor growth in vivo, highlighting the interest of its targeting in anti-cancer therapy." (PMID 29728578, 2018). "It was found that the tumours were heavier in mice injected with AAV-WT-lipin-1 mice compared to AAV-3YF-lipin-1 or AAV-control mice, although tumour onsets were similar among these groups." (PMID 33203880, 2020). "This RhoA activation in lipin-1-depleted cells could be related to the increased concentration of PA which can activate the sphingosine kinase-1 to produce sphingosine-1-phosphate, a lipid mediator able to enhance RhoA activity, and to inhibit migration of various tumor cells including PC-3." (PMID 25834103, 2015). "This is in line with our observations showing that lipin-1 is exclusively located in the cytoplasm and never in the nucleus of high-grade adenocarcinoma cells in tumor samples." (PMID 25834103, 2015). "It is conceivable that the presence or absence of lipin-1 in the neighbouring non-tumour cells would give rise to different compositions that would, in turn, alter contact between cancer and non-cancer cells or the contact between cancer cells and extracellular matrix." (PMID 33203880, 2020). "Untargeted lipidomic profiling on xenograft tumour samples revealed that the levels of PA were remarkably increased, while the levels of DAG were significantly decreased in nude mice implanted with LPIN1-KO MDA-MB-231 cells reconstituted with WT-lipin-1 or 3YF-lipin-1." (PMID 33203880, 2020).